KRT5 (keratin 5)
Diseases named in the same sentence as KRT5 in open-access papers (continued):
Sharing a sentence is not in itself a finding about the gene and the disease.
cancer (continued). "In addition, promoter hypomethylation of KRT5 and MMP7 genes was confirmed in cancer samples." (PMID 31569550, 2019). "Interestingly, HBME-1, cytokeratin 5/6 and thrombomodulin were differentially expressed in the spheroid in only a few cancer cells, but not in others." (PMID 21305058, 2011). "A negative correlation exists between survivin and keratin-5 in ER-positive breast cancers most probably because other transcriptional and nontranscriptional mechanisms are likely to control survivin expression in nonbasal cancers." (PMID 19025652, 2008). "For example, although the keratin genes (KRT5, KRT14, and KRT17) were found to interact in cancer genome studies, it was not clear how the cluster affects clinical features for cancer." (PMID 37395630, 2022). "As ER, PR, and HER2 result absent, these tumors may also be classified as “triple-negative” but lacking Cytokeratin 5 (CK5) and EGFR, they cannot be considered basal-like cancers as TNBC." (PMID 39287890, 2025).
adenocarcinoma (88 papers, 2004 to 2026). A common cancer characterized by the presence of malignant glandular cells. "Consistently, EP1 and EP2 show high expression of KRT7 and low expression of KRT5 at protein level, further supporting the adenocarcinoma origin." (PMID 41356800, 2026). "Biomarkers that are most commonly used for this purpose include mesothelial (calretinin, D2-40, WT1 and cytokeratin 5/6), epithelial (Claudin 4), and adenocarcinoma markers (Ber-EP4, TTF-1, CEA, MOC31, Napsin A)." (PMID 36292206, 2022). "The expression of two proteins, Cytokeratin 5 and c-Myc, was significantly different between all squamous cell and adenocarcinomas, both in fresh frozen and in FFPE samples." (PMID 32601356, 2020). "For BALB/c mice administered DMBA by gavage, most tumors have a remarkably consistent appearance by histological criteria (out of 19 analyzed, 17 were KRT5-positive), and are described as adenocarcinomas with acinar differentiation." (PMID 22347416, 2012). "In all cases of adenocarcinoma studied, loss of expression of both S100A6 and cytokeratin 5 was seen in the malignant cells." (PMID 15280928, 2004). "Activated EGFR was reported to induce keratin 5 and keratin 14 expression and was associated with the keratin expression percentages in the immune class, while the non-immune class was mostly composed of adenocarcinomas." (PMID 33971902, 2021). "When used in conjunction with cytokeratin 5/6 (CK5/6) and p63, this triad achieves a classification accuracy of 96.2% (94.6% for adenocarcinoma, 97.6% for SCC)." (PMID 41458151, 2025). "To do this, we compared DTumors (induced by orogastric gavage; KRT5-positive) with tumors induced by intraperitoneal injection of DMBA into BALB/c mice (typically undifferentiated adenocarcinomas; KRT5-negative)." (PMID 22347416, 2012). "Then, by staining for squamous epithelium markers (including KRT5, KRT6A, SFN, and KRT14) and columnar epithelium markers (including EPCAM and KRT8), groups 3, 7, and 10 were identified as squamous cancer cells, and groups 5, 6, and 8 were identified as adenocarcinoma cells." (PMID 36052088, 2022). "In addition, epithelial cells of patient #6 consisted of a group of NE cells (cluster 4, expressing ASCL1, CHGA, and CHGB), a group of basal cells (cluster 8, expressing KRT5, KRT14, and KRT15) as well as the remaining ARhigh luminal cells, presenting mixed features of both adenocarcinoma and NEPC." (PMID 33328604, 2020).
infection (45 papers, 2008 to 2025). The state of being infected such as from the introduction of a foreign agent such as serum, vaccine, antigenic substance or organism. "We observed 50% survival by post-infection day 14, a modest recruitment of neutrophils, and the presence of patchy Krt5 and Krt8 staining in lungs that also contained regions of normal alveolar structure." (PMID 40494897, 2025). "Their lungs contained numerous neutrophils on post-infection day 3 and extensively injured Krt5+ and Krt8+ fibrotic alveoli." (PMID 40494897, 2025). "Consistently, administration of baricitinib into IAV-infected mice from day 7 to day 11 after infection resulted in reduced KRT5+ alveolar area." (PMID 39352385, 2024). "Through comparing different lung-injury models, we demonstrated that infection induced strong IFN-γ signal–stimulated dysplastic KRT5+ cell formation." (PMID 39352385, 2024). "By day 18 after infection, only a limited number of dysplastic KRT5+ cells were found expressing activated Src." (PMID 39352385, 2024). "Consistently, oral delivery of FAK antagonist (PND-1186) or Src antagonist (saracatinib) into IAV-infected mice from day 7 to day 11 after infection resulted in reduced KRT5+ lung areas compared with control mice receiving PBS." (PMID 39352385, 2024). "The induction of epithelial progenitor activity was comparable in young and aged mice during the acute phase of infection (up to 14dpi) but diverged at later timepoints with increased Krt5+ and Krt8hi cells in aged mice." (PMID 38077031, 2023). "Next, we assessed expansion of Krt5-immunoreactive BC as a function of damaged area in IL-22 LOF mice following PR8 infection." (PMID 37726288, 2023). "During infection, basal cells proliferate and form nascent, discrete Krt5+ “pods” in the consolidation lung regions after Flu infection and contribute to epithelial recovery in the lung parenchyma." (PMID 38092883, 2023). "To assess if reduced BC hyperplasia observed in IL-22 LOF mice was associated with reduced epithelial proliferation, we measured the BC proliferative index by immunofluorescence of Ki67 and Krt5 following PR8 infection." (PMID 37726288, 2023). "Some up-regulated genes at 21 dpi (e.g., Ltf, Cxcl9, Pglyrp1, Prg2, Cxcl13, Cxcl3, Ccl9, Ccl19, Krt5, Krt14, Krt15, Krt17, and Slpi) were also identified in a previous infection study by using H1N1(PR8)." (PMID 38005876, 2023). "Injured alveolar regions were repopulated exclusively by basal-like Krt5-immunoreactive cells that were Lin3a2-low at day 14 post-infection." (PMID 37726288, 2023). "Consistently, we did not detect a significant difference in the percent of proliferating (Ki67+) alveolar Krt5+ basal-like cells at 14 or 25 days post infection." (PMID 36073526, 2022). "Using a flow cytometry quantitative approach, we found that at 60 days after infection, aged mice exhibited a significant increase in Krt5+ cells compared with young animals." (PMID 33600379, 2021). "Despite the loss of cilia on the apical surface, swIAV-H1N1-infected PBEC that had survived infection were positive for KRT5." (PMID 28004801, 2016). "The co-expression of Krt5 and Krt10 was unique to infection-specific clusters (clusters 0 and 6)." (PMID 38767331, 2024). "A major deficiency of the SARS-CoV-2 mouse infection model is the absence of persistent Krt8hi and Krt5+ areas of dysplastic repair – a hallmark of human PASC-PF." (PMID 38077031, 2023). "On the other hand, KRT5-positive basal cells survived 7 days after the infection." (PMID 35637255, 2022). "In IAV-exposed tracheobronchial ALI tissues, we observed viral antigen presence within multiple cell types at 24 h post-infection (hpi), with basal cells (KRT5+) being the dominant infected cell type, followed by ciliated cells (α-tubulin+) and goblet cells (MUC5AC+)." (PMID 35962146, 2022).
infection (continued). "From 5 to 25 days post-infection (dpi), mouse lungs were subjected to histopathologic and immunofluorescence analysis to probe for global distribution of lung repair cells (using P63 and KRT5 markers for DASCs; SPC and PCNA markers for AT2 cells)." (PMID 31455003, 2019). "(E) Lineage tracing shows about 80% of tuft cells are derived from EBCs in the lung parenchyma of KRT5-CreERT2;R26Ai14 mice following PR8 infection." (PMID 36129169, 2022). "To support our flow cytometry analysis, we collected mice 14 days post-infection with Mal/04-Cre and cross-sectioned tracheas to stain for the epithelial markers SSEA-1, KRT5 and FOXJ1 using microscopy." (PMID 30770807, 2019). "Consistent with our qRT-PCR analysis, infection of HDFn cells with ΔNp73β in combination with KLF4 + ΔNp63α led to increased expression of KRT14, KRT5, FLG, and SFN as compared to KLF4 + ΔNp63α with control or control alone." (PMID 31216312, 2019). "In the damaged areas, proliferation is maximal at 11 days post-infection and is driven by CD104-positive keratin 5-positive distal basal cells." (PMID 26048572, 2015). "Krt5‐CreERT2; Il33fl/fl‐mediated basal ESC‐specific ablation showed that the homeostasis in the gut and skin was disrupted, but remodeling and inflammation were downregulated in postviral infection of the lung." (PMID 41318981, 2025). "Thus, in response to infection-induced IFN-γ signal, dysplastic KRT5+ cells activate FAK/Src-YAP signaling to proliferate and migrate to the injured lung alveoli." (PMID 39352385, 2024). "To further investigate the intracellular signaling pathway by which IFN-γ regulates the formation of dysplastic KRT5+ cells, we performed single-cell RNA-sequencing (scRNA-Seq) assay on lung epithelial cells isolated from IAV-infected mice at day 14 after infection." (PMID 39352385, 2024). "Tamoxifen was administered at day 21 after infection, when most of KRT5+ cells had migrated into the alveoli and no longer expressed Ki67, and the mice were analyzed at 14 days after tamoxifen administration." (PMID 39352385, 2024). "In the absence of neutrophils and infection the airways comprise of a typical airway epithelium with KRT5+ basal cells residing on the basolateral surface and ciliated cells lining the airway lumen." (PMID 37006263, 2023). "A reduction in Krt5+ BC hyperplasia was observed in IL-22 LOF mice compared to WT control mice at all time points examined, which reached statistical significance by the day 17 post-infection time point." (PMID 37726288, 2023). "The study shows, by comparing CoV2 vs flu infection, that CoV2 infection fails to induce of Krt5+ “pod” formation and cell proliferation and mediates more profound chronic effects on the lungs including fibrotic abnormalities than flu infection." (PMID 38092883, 2023). "The infection rates increased in KRT5- differentiated epithelium (i.e., ciliated, goblet and club cells) (not significant) and in KRT5+ basal cells in the presence of neutrophils (p<0.001)." (PMID 37006263, 2023). "To address if a relatively minor population of Krt5+ cells may be converting to AT2s, we double stained for Krt5 and the AT2 cell marker SPC+ in Pou2f3-/- and control lungs at 25 days after infection to label cells in the process of conversion." (PMID 36073526, 2022). "Three days after infection of the HDFn cells with ΔNp73-expressing lentivirus, we harvested cells, isolated RNA, and performed qRT-PCR for keratinocyte genes that are markers of the iKC state (KRT14, KRT5, SFN, and FLG)." (PMID 31216312, 2019). "Interestingly, upon infection with H1N1, KRT5+p63+ cells also accumulate in the distal parts of mouse lungs, forming clusters or pods." (PMID 27423691, 2016). "Interestingly, these infection-induced KRT5+ progenitor cells do not differentiate into alveolar cell types but give rise to tuft cells and goblet cells in the injured alveoli." (PMID 39676102, 2024).
infection (continued). "Interestingly, Krt5-immunoreactive pods observed in lungs of either IL-22 LOF or IL-22r cLOF mice 14 days post-PR8 infection displayed evidence for Scgb3a2 expression that was absent in comparable Krt5-immunoreactive pod structures of wildtype control mice." (PMID 37726288, 2023). "Krt5 pods derived from DASCs were associated with lung regeneration as evidenced by the evolution of Krt5 pods into alveolus‐like structures during infection and could be labeled by alveolus‐specific antibodies, although Krt5 pods were absent in both noninfected and severely infected models." (PMID 41318981, 2025).
KRT5 also shares sentences with these, for which no sentence is quoted: invasive ductal carcinoma (14 papers); adenosquamous carcinoma (9); pancreatic cancer (7); skin cancer (7); basal cell carcinoma (6); carcinoma in situ (6); lung (6); epidermolytic ichthyosis (5); lymphoma (5); mucinous adenocarcinoma (5); Prostatic adenocarcinoma (5); alopecia (4); carcinosarcoma (4); metastasis (4); mucoepidermoid carcinoma (4); neuroendocrine tumors (4); papillary carcinoma (4); thymoma (4); upper tract urothelial carcinomas (4); cutaneous melanoma (3); epithelial dysplasia (3); gastric cancer (3); hepatocellular carcinoma (3); metastatic carcinoma (3); pachyonychia congenita (3); salivary gland tumors (3); small cell carcinoma (3); small cell lung carcinoma (3); sweat gland carcinoma (3); trichoblastoma (3).
A further 194 diseases each share a sentence with KRT5 in 3 papers or fewer.